MTOR (mechanistic target of rapamycin kinase)
Diseases named in the same sentence as MTOR in open-access papers (continued):
Sharing a sentence is not in itself a finding about the gene and the disease.
cancer (continued). "As the application duration increased, a fluctuation in mTOR activity was observed in MM cancer stem cell lines, while LC3 activity steadily increased, with a greater increase observed in the MM cancer cell line after 10 min of application." (PMID 40561182, 2025). "The has‐circ‐0008234/miR‐338‐3p/ETS1 axis offers further evidence of circRNA‐mediated control of the PI3K/AKT/mTOR pathway, reinforcing its significance in cancer progression." (PMID 40740483, 2025). "Meanwhile, mTOR signaling plays a key role in cancer growth, angiogenesis, and metastasis formation." (PMID 40098014, 2025). "Several clinical trials have been conducted or are underway to evaluate the therapeutic efficacy of mTOR inhibitors, including everolimus and temsirolimus, in human cancers." (PMID 40563640, 2025). "PTEN reduces PIP3 levels, decreasing the mTOR/AKT signaling pathway critical for cancer cell growth, survival, and progression." (PMID 39754630, 2025). "Plum extract also influences the AKT/mTOR pathway and microRNA (miR-143), which are involved in cancer growth, thus suggesting chemopreventive potential for colon cancer." (PMID 40149274, 2025). "Research has found that ginsenoside CK can effectively inhibit the expression of AKT/mTOR/p70S6K1 proteins in cancer cells, block the PI3K/AKT/mTOR signaling pathway, and reduce the expression of MMP2 and MMP9 proteases." (PMID 40422575, 2025). "The PI3K/AKT/mTOR (PAM) signaling pathway is a classical pathway that is aberrantly activated in cancer cells and promotes the tumorigenesis, metastasis, resistance to castration therapy, chemoresistance, and recurrence of PCa." (PMID 40170845, 2025). "Blocking Survival Pathways: It inhibits the PI3K/Akt and mTOR pathways, which are crucial for cancer cell survival and growth." (PMID 40649942, 2025). "Though the role of the PI3K/AKT/mTOR pathway in the OC is complex, the dysregulation of this pathway increases the tumor formation, migration of cancer cells, and resistance to the current treatment methods like radiotherapy and chemotherapy." (PMID 38584538, 2025). "Capivasertib specifically targets and inhibits AKT, a key protein within the PI3K/AKT/mTOR pathway, which is crucial for cancer cells' survival and proliferation." (PMID 40308416, 2025). "This suboptimal effectiveness reflects not only the complexity of mTOR signaling in cancer but also specific mechanistic limitations inherent to the rapalog mechanism of action." (PMID 41469379, 2025). "The PI3K/Akt/mTOR pathway, dysregulated in nearly 60% of these cancers, appears to be a prime target." (PMID 40647529, 2025). "In fact, mTOR inhibitors have shown promise in the treatment of several non-cancer diseases due to their role in regulating cellular processes such as metabolism, immune response, and cell growth." (PMID 40299431, 2025). "The AKT/mTOR signaling axis is frequently hyperactivated in many types of cancer and is involved in key processes such as proliferation, metabolic adaptation, autophagy, and apoptosis." (PMID 39850502, 2025). "The inhibitory effect of VPA on the activation of the PI3K/Akt/mTOR pathway occurs through reducing the phosphorylation of Akt, leading to suppressed mTOR activity, decreased protein synthesis, and ultimately promoting apoptosis in cancer cells." (PMID 40283503, 2025). "In this work, we further demonstrate the 48aa-long hSPAR-C as the functional domain for hSPAR’s inhibitory effect on glutamine level control, mTOR signaling and cancer proliferation on both cultured cells and xenografic mice." (PMID 39875724, 2025). "Subsequent investigation has shown that mTOR is often active in neoplasms and governs cancer cell metabolism by regulating crucial metabolic enzymes." (PMID 40717210, 2025). "Previous evidences have shown that agents for cancer therapy that targeted mTOR can induce autophagy of cancer cells." (PMID 40771929, 2025).
cancer (continued). "Curcumin therapy, in conjunction with prior treatment with rapamycin and LY294002, enhanced starvation and death in cancer cells by inhibiting mTOR signaling." (PMID 40717210, 2025). "The PI3K/AKT/mTOR pathway is one of the most frequently dysregulated signaling pathways in cancer and plays central roles in the growth, proliferation, motility and survival of tumor cells." (PMID 40076586, 2025). "The botanical drug metabolites Ruscogenin, Sulforaphane, Naringenin, Kaempferol, Poncirin, and Puerarin can improve cancer by inhibiting the phosphorylation levels within the PI3K/Akt/mTOR signaling cascade." (PMID 40196368, 2025). "Metformin exerts its anti‐cancer effects on the mTOR pathway primarily by activating AMPK, a cellular energy sensor that responds to low ATP levels." (PMID 40387523, 2025). "Chitosan (CS) is a potential cancer therapeutic that mediates via PI3K/Akt/mTOR, MAPK and NF-kβ signaling pathway modulation." (PMID 40503054, 2025). "In the context of human disease, mTOR signalling touches upon nearly all aspects of medicine including immune disorders, cancer, metabolic disorders, neurodegeneration and neurodevelopmental diseases." (PMID 40426219, 2025). "Instead, hSPAR fulfills its mTOR inhibitory effect through acting as a cancer-specific metabolism regulator and P27KIP1 stabilizer." (PMID 39875724, 2025). "Phosphatidylinositol‐3,4,5‐trisphosphate (PIP3): The PI3K/Akt/mTOR signaling pathway plays a central role in cancer cell growth, survival, and metabolism." (PMID 40391753, 2025). "Although the anticancer effect of mTOR inhibitor, everolimus, was reported, a previous study demonstrated that it promotes treatment-related death in cancer patients." (PMID 40374533, 2025). "In a variety of malignant tumors, the mTOR signaling pathway is hyperactivated, resulting in inhibition of autophagy, which promotes the growth and proliferation of tumor cells." (PMID 41287122, 2025). "For example, the mTOR inhibitor vistusertib combined with ICIs such as αPD-1, αCTLA-4 and αPD-L1, produced synergistic anti-cancer effects compared to when these agents were administered individually." (PMID 40407951, 2025). "mTOR complexes play pivotal roles in cancer metabolism through intricate mitochondrial regulatory mechanisms." (PMID 40754534, 2025). "The PI3K/AKT/mTOR pathway is a central regulator of cell growth, survival, and metabolism and is frequently hyperactivated in numerous cancers." (PMID 41303544, 2025). "Inhibiting Notch signaling can reduce cancer cell aggressiveness by affecting other pathways, such as mTOR and NF-κB." (PMID 40003637, 2025). "Accordingly, targeting the PI3K/Akt-mTOR pathway to modulate tumor metabolism has emerged as a therapeutic strategy for cancers." (PMID 41219936, 2025). "It acts not only as a cargo receptor in autophagy, but is a multifunctional protein affecting several cellular key regulators in cancer development, including Nrf2, NF-κB, or mTOR." (PMID 40593496, 2025). "Cluster C was associated with immune-inhibitory or cancer-promoting pathways like TGF beta signaling, adherens junction, mTOR signaling, gap junction, and WNT signaling pathway." (PMID 39895799, 2025). "Lipid metabolic reprogramming has also been shown to interact with other signaling pathways, such as PI3K/Akt and mTOR, which are frequently hyperactivated in cancer cells." (PMID 40278350, 2025). "ICGA-A and CRA, bioactive compounds from Taraxacum officinale, exhibit significant antitumor activity in TNBC by targeting the FAK/PI3K/AKT/mTOR pathway, a critical regulator of cancer progression." (PMID 40109332, 2025). "This indicates that ATP production increases during the induction of FAO by autophagy in cancer cells, which then activates mTOR." (PMID 40848971, 2025). "Activation of AMPK by fasting also enhances autophagy and inhibits protein synthesis via mTOR suppression, further reducing the growth and survival of cancer cells." (PMID 39940361, 2025).
cancer (continued). "mTOR plays a critical role in regulating the balance between cell proliferation and autophagy in response to cellular stress in cancer cells." (PMID 40129995, 2025). "This method efficiently inhibits cancer cells from transitioning to an autophagy-dependent survival mechanism after mTOR inhibition." (PMID 40710325, 2025). "The HER2 + cancers, on the other hand, seemed to involve activation of another class of lipid kinases through MTOR." (PMID 40700427, 2025). "PSD acts as an autophagy flux inhibitor in various cancer cells and induces autophagosome initiation; it can serve as a chemosensitizer, where its inhibition of mTOR and phosphorylation of its downstream target p70S6K induces autophagosome formation." (PMID 41227351, 2025). "In the hepatic stellate cells, activating the PI3K/Akt/mTOR signaling pathway links to liver damage, such as fibrosis and cancer." (PMID 39968080, 2025). "For example, stiff matrices activate integrin β1-dependent AKT and mechanistic target of rapamycin (mTOR) signaling, reinforcing cancer stemness and reducing sorafenib-induced apoptosis." (PMID 41438763, 2025). "The PI3K/Akt/mTOR pathway is essential in regulating cellular growth, proliferation, migration, and survival, with hyperactivation often observed in various cancers, including breast, lung, and prostate cancer." (PMID 40084006, 2025). "The PI3K/Akt/mTOR and MAPK/ ERK signaling pathway is frequently activated in cancer and has been associated with resistance to chemotherapy and targeted therapies." (PMID 40287412, 2025). "Over 60% of HPV-induced cancers show mTOR phosphorylation (p-mTOR, Ser2448), correlating with increased tumor aggressiveness and metastasis." (PMID 40667502, 2025). "Downregulation of the mTOR pathway was noticed in cancer cells and is responsible for the slow cell cycle, dormancy, and drug resistance." (PMID 40148800, 2025). "It was shown that co-treatment with mTOR (master regulator of energy) inhibitors increased the anti-cancer effect of Aurora kinase B inhibitors in vitro in myeloid leukemia cell lines." (PMID 40117022, 2025). "Specifically, PTPN6 and PTPN11 are involved in the phosphoinositide 3 kinase/AKT/mammalian target of rapamycin (PI3K/AKT/mTOR) signaling pathway, which has been implicated in cancer progression and metastasis." (PMID 40806280, 2025). "Despite the regulation of the PI3K/AKT/mTOR axis and its impact on apoptosis and autophagy, the final role of autophagy in human cancers remains uncertain." (PMID 40740483, 2025). "It regulates cancer cell proliferation and migration by activating mTOR and ERK signaling pathways after binding to corresponding receptors." (PMID 41253786, 2025). "Dysregulation of AMPK and mTOR signaling pathways can profoundly impact tumor growth and progression, making them attractive targets for cancer therapy." (PMID 39969135, 2025). "The clinical development of mTOR inhibitors for cancer therapy has significantly advanced over the past two decades." (PMID 40821795, 2025). "mTOR is frequently activated in diverse carcinomas and also widely accepted as a master regulator for cell proliferation control." (PMID 39875724, 2025). "Database synthesis corroborated disease associations involving MTOR and its partners (e.g., TSC2, RICTOR, RPTOR, MLST8, AKT1 across selected carcinomas)." (PMID 41300706, 2025). "Consistent with findings in this study, cancer cells harboring activating mutations in the AKT pathway and its downstream mTOR signaling pathway exhibit resistance to ferroptosis." (PMID 39353906, 2024). "Emerging studies have underscored the pivotal importance of PRKCI in triggering Akt-mTOR activation within cancerous cells, revealing its potential as a crucial factor in cancer development and progression." (PMID 39015499, 2024). "In many cancers, the mTOR pathway is upregulated, possibly due to the dysregulated presence of leptin." (PMID 39596205, 2024).
cancer (continued). "LINC00963 can activate the oncogenic AKT/mTOR signaling pathway or EGFR signaling pathway to enhance cancer cell metastasis." (PMID 38615287, 2024). "PD-L1 signaling is closely associated with glycolysis in cancer cells and maintains AKT/mTOR signaling, supporting the translation of glycolytic enzymes." (PMID 38726017, 2024). "Based on accumulating evidence, STAT3 is a target gene downstream of AKT/mTOR signaling in cancer cells." (PMID 38183094, 2024). "PI3K/Akt/mTOR pathway renders a survival signal to withstand cytotoxic anticancer drugs and enhances cancer stem cell characteristics." (PMID 39443476, 2024). "Targeting SCD1 is considered a potential therapeutic strategy for cancers resistant to ferroptosis induction, particularly those with mutations in the PI3K/AKT/mTOR pathway." (PMID 38562143, 2024). "TMES3 strongly upregulated fatty acid metabolism, cancer-related pathways, cytokine pathways, and the mTOR pathway." (PMID 38565865, 2024). "The convergent surviving cell gene set we identified indicated that pro-survival and anti-apoptotic pathways, such as TNFa via NFkB, PI3K-AKT, and mTOR signaling, are upregulated in polyploid cancer cells." (PMID 39483900, 2024). "Our research probes the mechanistic role of HSP90B1 in regulating the PI3K/Akt/mTOR pathway, a key downstream effector of EGFR signaling implicated in the oncogenesis of various cancers." (PMID 38711062, 2024). "Curcumin’s action on mTOR can help restore autophagic processes, potentially leading to cancer cell death." (PMID 39056768, 2024). "Dysregulation of the PI3K/AKT/mTOR signaling pathway is frequently observed in cancers, and leads to pleiotropic effects, including modulation of autophagy, epithelial–mesenchymal transition (EMT), apoptosis, chemoresistance, cell survival, and metastasis." (PMID 39123348, 2024). "The PI3K/AKT/mTOR signaling pathway has been found to play a vital role in regulating the migration and invasion of cancer cells." (PMID 38474604, 2024). "While additional tests are required, the data presented here would suggest exposure to FSS-induced mTOR signaling in the metastatic setting in HR+ cancer cells with WT ER." (PMID 39000231, 2024). "The various members of the PI3K/mTOR/AKT signaling pathway display a variety of gain of function and loss of function mutations that, alone or in combination, are key drivers for cancer growth." (PMID 38539472, 2024). "In cancer, PIK3CA is most frequently mutated, with mutations in AKT1, AKT2, and the proteins of the mTOR complex, except for RICTOR and mTOR, being relatively uncommon." (PMID 38473265, 2024). "Due to its importance in regulating autophagy, the mTOR pathway is widely studied as a target for therapeutic avenues in cancers and M. tb infections." (PMID 39457551, 2024). "The BEZ235 dual PI3K/mTOR inhibitor has been reported to exhibit excellent anti-cancer effects in many types of cancer including melanoma, colorectal, lung, renal, breast, and prostate cancer." (PMID 39410536, 2024). "Activation of the PI3K-Akt-mTOR signaling pathway is essential to the survival, proliferation, migration, and invasion of various cancer cells." (PMID 39334689, 2024). "PD-L1 expression in cancer cells can activate the Akt-mTOR signaling axis, enhance glycolysis, prompt glucose competition between the tumor and T cells, and increase lactate production." (PMID 39539540, 2024). "PI3K/AKT/mTOR is often up-regulated in aggressive cancers but is down-regulated in the cluster group with shorter PFS." (PMID 39591314, 2024). "As a whole, these studies have illustrated that metformin plays an anti-cancer stem-like role in GBM cell lines via the AKT/mTOR/ZEB1 pathway." (PMID 39267853, 2024). "Pan-cancer analysis of TCGA data revealed that SF3B3 expression correlated positively with the expression of full-length mTOR-001 isoform." (PMID 38671459, 2024).
cancer (continued). "Regulatory mechanisms on AMPK expression have been seen in cancer cells along with key signaling molecules such as mammalian Target Of Rapamycin (mTOR) (Raptor) or Hypoxia-Inducible Factor 1-alpha (HIF-1α) which control AMPK protein expression." (PMID 38555305, 2024). "The phosphoinositide 3‐kinase (PI3K)/protein kinase B (AKT)/mammalian target of rapamycin (mTOR) signaling pathway is one of the most frequently deregulated pathways in human cancer and a key regulator of cellular proliferation, growth, and survival." (PMID 38400671, 2024). "The interference with these vital cellular processes significantly diminishes the effectiveness of mTOR inhibitors in cancer treatment." (PMID 38476632, 2024). "Among these pathways, the mTOR pathway is particularly noteworthy for its significant role in activating not only stem cells but also immune cells within cancer tissues." (PMID 39349424, 2024). "The PI3K/Akt/mTOR pathway plays an important role not only in controlling the proliferation and apoptosis of cancer cells but also in promoting normal and tumor angiogenesis." (PMID 39335919, 2024). "Employing both ex vivo and in vivo HCC models, we further elucidate the critical role of SMYD5-mediated RPL40 K22me3 in sustaining cancer growth, especially under suppressed mTOR signaling." (PMID 39103523, 2024). "In vitro studies have suggested that human ERMP1 increases the proliferation and invasion of cancer cells through the PIK3/AKT/mTOR/β-catenin pathway." (PMID 38785548, 2024). "Rapamycin, a pharmacological mTOR inhibitor used as an immunosuppressive drug in transplantation, has also been widely evaluated for the treatment of many cancers." (PMID 38791040, 2024). "Clinical research has demonstrated that PAK1 not only participates in the tumorigenicity of diverse cancers but also modulates autophagy levels through the Akt/mTOR or Erk/mTOR signaling pathway." (PMID 38956466, 2024). "The mechanistic inhibition of the mTOR pathway was demonstrated to be an effective strategy for generating a quiescent state in embryonic stem cells, stem cells, and cancer cells." (PMID 38418814, 2024). "The role of AMPK as the cell’s primary metabolic hub, which is activated whenever the AMP/ATP ratio is high, has been found to suppress the growth of a number of cancer cells as well as the mammalian target of rapamycin (mTOR) signaling pathway." (PMID 38746670, 2024). "As for mTOR pathway is very complex and different tumor cells have different sensitivity to rapamycin, rapamycin alone has a low success rate in inhibiting cancer cell proliferation." (PMID 38583115, 2024). "Targeting mTOR and inducing autophagic cell death downstream of it represent promising therapeutic strategies for cancer prevention." (PMID 39513392, 2024). "Dysregulated lysosomal activity and mammalian target of rapamycin (mTOR) complex 1 signaling has been shown to play a role in the development of resistance to chemotherapy and targeted therapies in cancer cells." (PMID 39267840, 2024). "Our results in vivo demonstrate that use of PI3K/mTOR inhibitors alone are effective at suppression of cancer cells proliferation, but ineffective as a method for elimination of cancer cells." (PMID 40115434, 2024). "ERBB2 is a member of the epidermal growth factor receptor family and functions upstream of signaling pathways frequently implicated in cancer, such as the MAPK or the mechanistic target of rapamycin (mTOR) signaling pathways." (PMID 38778091, 2024). "Further investigation of how ISO targets key molecules and pathways such as HIF1a signaling and the PI3K/AKT/mTOR pathway to facilitate its cancer inhibitory effects, is necessary for maximizing its effectiveness as a cancer therapeutic drug." (PMID 38339062, 2024). "The PI-3K/Akt/mTOR pathway plays a crucial role in the process of EMT during the development of cancer." (PMID 39204369, 2024).